NLRP3 (NLR family pyrin domain containing 3)
Diseases named in the same sentence as NLRP3 in open-access papers (continued):
Sharing a sentence is not in itself a finding about the gene and the disease.
tumor (continued). "In studies that demonstrated a positive association, NLRP3 deficient mice presented more inflammation and higher tumor burden compared to controls." (PMID 23606794, 2013). "Furthermore, CAFs can respond to damage-associated molecular patterns (DAMPs) released by necrotic tumor cells, activating the NLR family pyrin domain containing 3 (NLRP3) inflammasome and propagating tumor-promoting inflammation." (PMID 40427384, 2025). "Activation of NLRP3 may enhance M2 polarization of tumor-associated macrophages, thereby promoting tumor metastasis and growth." (PMID 40535567, 2025). "In a separate study, NLRP1/NLRP3 expression was linked to poor overall survival, advanced stage, the development of lymph node metastases, and the infiltration of immune cells in the tumour microenvironment." (PMID 41148809, 2025). "However, following this period, there was a notable shift in focus toward metabolism, tumor-associated macrophages, NLRP3 inflammasome, and, subsequently, autophagy, tissue-repair, and polarization." (PMID 40242756, 2025). "Additionally, NLRP3 inflammasome has been identified as a factor that promotes cancer progression by influencing various processes involved in tumor development, with its activation linked to cancer metastasis." (PMID 40135589, 2025). "M1 macrophages, associated with a pro-inflammatory and anti-tumor phenotype, typically exhibit higher levels of NLRP3 activity, while M2 macrophages are characterized by reduced NLRP3 activity, consistent with their anti-inflammatory profile and tumor-promoting effects." (PMID 40002754, 2025). "Deficiency of myeloid NLRP3 promoted tumor burden and inhibited NK cell activation." (PMID 40075527, 2025). "In mice, Nlrp3 deficiency has been linked to fewer lung metastases in an orthotopic tumor model." (PMID 40195474, 2025). "We hypothesized that the Toe-Macs in NSCLC are pathogenic, in part due to enhanced expression of the key tumor-promoting factors NLRP3, IL-1β, TGF-β1, CCL2, IL-6, and PD-L1 (encoded by CD274)." (PMID 40794443, 2025). "Future studies could design large-scale cohort studies to assess the diagnostic value of combining NLRP3 inflammasome levels with classic tumor biomarkers such as AFP and CA-125." (PMID 40718836, 2025). "The strong co-expression of ALKBH7 and NLRP3 suggests a functional association between these molecules that may be critical in shaping the tumor microenvironment." (PMID 41373809, 2025). "A study reported that Akkermansia muciniphila (A. muciniphila) had the capacity to bind to the macrophage pattern recognition receptor TLR2, activating the NF-kB/NLRP3 pathway, promoting the shift towards M1-like tumor-associated macrophages (TAMs), and inhibiting colon tumorigenesis." (PMID 40520902, 2025). "Therefore, in myeloid cells, PEFs primarily modulate MDSCs through the NLRP3/IL-1β signaling pathway and regulate tumor-associated macrophages via the CCLs/CCR2 signaling axis." (PMID 41357174, 2025). "Pharmacological inhibition of NLRP3 inflammasome using MCC950, followed by PTX administration decreased the pro-inflammatory processes associated with anti-tumor treatment as indicated by the expression of NLRP3, caspase-1, IL-1β and IL-18, compared with PTX treatment." (PMID 39433537, 2024). "It is tempting to speculate that NLRP3-induced increased expression of coinhibitory molecules such as PD-L1 on intraspheroidal macrophages and tumor cells is causing the slight decrease in spheroid rejection that was observed in our spheroid model." (PMID 39796680, 2024). "The antigens CARD8, NAIP, NLRP1, and NLRP3, which are associated with tumor pyroptosis, could be candidate molecules for LUAD mRNA vaccine development." (PMID 38166691, 2024). "NLRP3 activates caspase-1, which then cleaves immunological and metabolic substrates, including the pro-inflammatory cytokine interleukin-1b (IL-1β), which causes inflammation and promotes tumor growth." (PMID 37715239, 2023).
tumor (continued). "In addition, NLRP3-deficient MDSCs (isolated from knockout tumor-bearing mice) are less efficient in reaching the tumor site." (PMID 36911674, 2023). "Furthermore, mice that received intravenous implantation of NLRP3‐deficient HCC cells exhibited significantly reduced tumor growth and lower rates of metastasis compared with mice implanted with normal HCC cells." (PMID 38116060, 2023). "NLRP3 activation inhibition caused by miR-233 inhibits tumor cell growth, migration, and invasion." (PMID 37300757, 2023). "Besides, NLRP3 activation and IL-1β secretion have been linked to tumor growth, invasiveness, relapse, and progression in recent studies." (PMID 37715239, 2023). "Direct inflammasome activation within the tumor may be an important mechanism for engaging antitumor immunity because NLRP3 activation causes pyroptotic, immunogenic cell death and the release of pro-inflammatory factors." (PMID 37715239, 2023). "First, we investigated whether NLRP3 inflammasome was activated in the tumor-bearing lungs of NR1D1-deficient mice." (PMID 37524704, 2023). "In addition, NLRP3 inflammasome can modulate the recruitment and polarization of tumor-associated macrophages (TAMs) and myeloid-derived suppressor cells (MDSCs), which secrete proinflammatory cytokines and chemokines that support tumor growth and progression." (PMID 37715239, 2023). "The function of NLRP3 in specific tumors may also be affected by the effects of other mutations on its expression, tumor type, tumor stage, and effector molecules downstream of NLRP3." (PMID 37715239, 2023). "We first investigated whether NLRP3 deficiency in gp130F/F mice impacted on tumor-associated inflammation." (PMID 35299732, 2022). "In addition, expression of Cd274 gene (known as PDL1), closely linked to tumor immune evasion, was downregulated in Nlrp3-/- G-MDSCs." (PMID 36032139, 2022). "A clinical study showed that NLRP3 inflammasome activation exhibits a protective effect on the development of HCC, but other experimental data indicated that NLRP3 deficiency in HCC cells enhance surveillance of NK cells to delay the tumor development in the xenograft mice model." (PMID 36160411, 2022). "Bioinformatic analyses identified NLRP3-inflammasome-related genes that were differentially expressed between normal and tumor samples in 15 cancer types and were significantly associated with survival of patients with hepatocellular carcinoma or skin cutaneous melanoma." (PMID 35739593, 2022). "After the NLRP3 inflammasome is activated, it cannot produce self-inhibition even in a resting state, which results in the continuous production of IL-1β and IL-18, finally causing long-term effects on inflammation and tumor diseases." (PMID 35292015, 2022). "TUNEL staining of transplanted tumour tissues indicated that luteolin might cause apoptosis, while NLRP3/GSDMD colocalization staining indicated that luteolin could also cause pyroptosis." (PMID 36105214, 2022). "Indeed, NLRP3 has been shown to be overexpressed by many cancers, while elevated levels of tumor NLRP3 expression have also been associated with an inferior clinical prognosis." (PMID 34638239, 2021). "However, in pancreatic ductal adenocarcinoma, interleukin (IL)-10-dependent NLRP3 signaling was shown to be involved in inducing immunosuppressive microenvironment formation by promoting tumor-associated macrophage expansion." (PMID 34805183, 2021). "Furthermore, in vivo experiment using xenograft mouse model, the NLRP3-deficient HCC cells delayed the tumor development and metastasis as well as interestingly enhanced a sensitivity of NK immunosurveillance in mice." (PMID 34502191, 2021). "The NLRP3 inflammasome deficient mice are more susceptible to colitis-induced colorectal cancer due to reduced production of IL-18, and subsequent inactivation of tumor suppressor STAT1." (PMID 34210954, 2021).
tumor (continued). "As NLRP3 activation causes pyroptotic, immunogenic cell death and the release of pro-inflammatory factors, direct inflammasome activation within the tumor may be an important mechanism to engage antitumor immunity." (PMID 33840390, 2021). "Tumor growth was nearly the same in NLRP3-deficient mice as in WT mice." (PMID 33649199, 2021). "Nevertheless, the inflammatory pathways are also affected by immune checkpoint inhibitors, nivolumab and ipilimumab, that caused changes in NLRP3 inflammasome, MyD88 complex NF-κB/p65 expression, and in several interleukins in co-cultures of lymphocytes with tumor or with cardiac cells." (PMID 34073506, 2021). "Whether germline genetic alterations contribute significantly to tumor-intrinsic NLRP3 functionality or whether the activation of tumor-intrinsic NLRP3 is dominantly controlled by tumor somatic mutations also remains unclear." (PMID 34638239, 2021). "In vivo, the loss of NLRP3 inflammasome or caspase-1 activity has been found to inhibit the priming and activation of CTLs, thereby significantly blocking the cytotoxic effects of CTLs against tumour cells in mouse models." (PMID 33918087, 2021). "Moreover, NLRP3 activation and IL-1β production are associated with tumor lymphangiogenesis and lung metastasis in BC." (PMID 33014808, 2020). "NLRP3 is expressed in cells from the myeloid lineage, such as monocytes, macrophages, myeloid-derived suppressor cells (MDSCs), and Tumor-associated macrophages (TAMs), which may have a dual role during tumorigenesis." (PMID 33014808, 2020). "Analysis of immune cell infiltration in tumours injected with WT vs. inflammasome-deficient fibroblasts indicated that attenuated tumour growth and metastasis in mice in which NLRP3/IL-1β were knocked down, was associated with reduced recruitment of CD11b+Gr1+ myeloid cells." (PMID 31558756, 2019). "Inhibition of the NLRP3 inflammasome was seen to reduce tumor burden in the murine model of colitis-associated cancer, with the increased tumor burden correlating with attenuated levels of IL-1β and IL-18 at the tumor site." (PMID 31231372, 2019). "Interestingly, high-fat diet has also been associated with NLRP3 activation and increased tumor susceptibility." (PMID 30837326, 2019). "Notably, the triggering of tumor-associated pDCs with the NLRP3 activator caused elevated IL-1β levels." (PMID 30447690, 2018). "The mouse models using an oxalate diet promote kidney damage and result in NLRP3 activation; however, the data is inconsistent on whether NLRP3 deficiency is a risk factor for tumor formation due to the inflammatory response." (PMID 30447690, 2018). "Similarly, in a breast cancer model, deficiency of inflammasome components (NLRP3 or caspase-1 knockout) reduced tumor growth and metastasis and was correlated with reduced infiltration of MDSCs within the tumors." (PMID 30631327, 2018). "Moreover, the capacity of PTX to modulate the NLRP3 inflammasome, in the TNBC context, has been investigated, and the obtained data highlighted that NLRP3 pre-treatment facilitated the effects of PTX on tumor cells, therefore reducing the cancer-associated inflammation." (PMID 39940603, 2025). "Toll-like receptor 4 (TLR4) pathways and the NLRP3 inflammasome are aberrantly activated by pollutant components, leading to excessive IL-1β maturation and skewing alveolar macrophages towards a tumor-associated phenotype that supports immune evasion and tumor progression." (PMID 41345682, 2025).
tumor (continued). "Furthermore, analysis of cytokine expression and the migration and proliferation profiles of PC3 cells indicated that PC3-EVs impact differentiated THP-1 macrophages, showing that PC3 cells contain an active NLRP3 inflammasome cascade and secrete IL-1β, which is associated with tumor staging." (PMID 40718836, 2025). "Hence, herein, we speculated that melatonin potentially alleviates tumor-associated angiogenesis and lymphangiogenesis using the NLRP3 axis." (PMID 39230586, 2024). "Furthermore, NLRP3 inflammasome can influence the attraction and differentiation of tumor-associated macrophages (TAMs), which produce proinflammatory cytokines and chemokines that facilitate tumor growth and blood vessel formation." (PMID 37715239, 2023). "On the other hand, a large number of cytokines, cell contents, and DAMPs released by necroptosis may trigger the NF-kappaB pathway and initiate and activate the NLRP3 inflammasome, which can cause a robust inflammatory response and immunosuppression to promote the tumor growth and metastasis." (PMID 37760507, 2023). "Moreover, chemotherapy treatment of tumor cells (e.g., with oxaliplatin and anthracyclines) can cause tumor cells to release ATP, which is an activation signal for the NLRP3 inflammasome and the IL-1β/IL-1 receptor (IL1R) signaling axis in dendritic cells (DCs)." (PMID 37497237, 2023). "However, NLRP3 functions as a tumor suppressor and protects against colitis-associated cancer." (PMID 36541912, 2022). "Although presence of IL-1β has been closely linked to tumor progression and metastasis in various types of cancer, the role of NLRP3 inflammasome activation remains controversial, suggesting that other functional roles of inflammasome, beyond secretion of pro-inflammatory mediators, may exist." (PMID 36032139, 2022). "Therefore, considering our observation that in NLRP3-deficient mice tumor progression was stunted, we hypothesized that the infiltrating myeloid cells were propagating pro-tumor signaling." (PMID 35631400, 2022). "Therefore, we sought to assess whether tumor-associated NLRP3 activity also affects the IL-1β/IL-6/STAT3 axis in host myeloid cells." (PMID 34531850, 2021). "The anti-tumor role of inflammasomes has been extensively studied in colitis-associated cancer, showing that the secretion of IL-18 mediated by the NLRP3 inflammasome could protect enterocytes from early-stage colitis induced by dextran sulfate sodium (DSS) or azoxymethane (AOM)." (PMID 34298833, 2021). "In addition, NLRP3 inflammasome in fibroblasts is further linked with progression and metastasis, and IL-1β was found to have an immunosuppressive, pro-tumorigenic in the tumor microenvironment." (PMID 32733479, 2020). "To determine whether IOP activation of the NLRP3 inflammasome is causally related to its anti-tumor activity, we examined the effects of NLRP3 inflammasome inhibition (using a small molecule inhibitor MCC950) or activation (transfected NLRP3 overexpressed plasmid) on the growth of SW620 cell." (PMID 33603669, 2020). "Comparisons between OSCC tissues and normal oral mucosa consistently reveal elevated expression of NLRP3, caspase-1, and IL-1β, which correlate with advanced tumor stage, lymph node metastasis, and poor clinical prognosis." (PMID 41596738, 2026). "NLRP3 activation within tumor cells enhances proliferative and survival signaling through IL-1R–mediated autocrine and paracrine loops, promotes epithelial–mesenchymal transition (EMT), and increases resistance to apoptosis." (PMID 41596738, 2026). "NLRP3, a key component of the inflammasome complex, is known to promote inflammation and tumor progression by activating proinflammatory cytokines." (PMID 41479846, 2025). "Another study demonstrated that CRT was involved in the NLRP3 activation signal, most likely via the alteration of Ca2+ homeostasis in tumor cells." (PMID 39857785, 2025).
tumor (continued). "Efferocytosis directly activates signaling of NLRP3 inflammasome, thereby driving IL‐1β secretion, which promotes tumor growth." (PMID 39748782, 2025). "(2021) showed that Akkermansia muciniphila (A. muciniphila), a bacterium naturally found in the human gut, triggers TLR2 dependent NF-kB/NLRP3 pathways in M1-like macrophages to inhibit tumor growth." (PMID 40692785, 2025). "The production of IL‐1β and caspase‐1 after NLRP3 activation in TAMs contributes to the formation of an inflammatory tumor microenvironment, which facilitates tumor metastasis." (PMID 40671401, 2025). "Uric acid–induced NOD-, LRR-, and pyrin domain-containing protein 3 (NLRP3) activation and neutrophil infiltration further reinforced this tumor-promoting milieu." (PMID 41470234, 2025). "Our relevant studies demonstrated that inhibiting NLRP3 expression significantly elevated E-cadherin expression while reducing Vimentin expression in tumor cells, suggesting suppressed EMT progression." (PMID 39744485, 2025). "Another study demonstrated that knockdown of NLRP3 led to reduced xenograft tumor growth in prostate cancer in in vivo model." (PMID 41410801, 2025). "The attenuated hematopoietic cell-derived IL-1β and IL-18 at the tumor site of Nlrp3-knockout (Nlrp3−/−) mice are found to be the key to inflammation and tumorigenesis." (PMID 40141358, 2025). "Dapansutrile enhances anti-tumor immunity by restricting the expansion of myeloid-derived suppressor cells (MDSCs), an effect mediated through its selective inhibition of the NLRP3 inflammasome in tumor cells." (PMID 41415576, 2025). "Mutations also affect the function of NLRP3 in specific tumors by affecting tumor type, tumor stage, and effector molecules downstream of NLRP3 signaling." (PMID 41560727, 2025). "There is considerable potential for the discovery of effective therapies that selectively target NLRP3 inflammasome activation pathways and thereby control tumor formation and progression." (PMID 40671401, 2025). "This transformation involves an increased presence of myeloid cells (CD11b+Ly6ChighLy6G−) in the tumor, driven by the NLRP3." (PMID 41291696, 2025). "NLRP3 can also accelerate head and neck cancer tumor progression by activating cancer stem cells (CSCs) and inducing CSCs to self‐renew." (PMID 40671401, 2025). "This stimulates NF-κB-mediated transcription of pro-inflammatory cytokines and contributes to mitochondrial ROS production, further amplifying NLRP3 inflammasome activation and reinforcing the inflammatory state of the tumor microenvironment." (PMID 40869140, 2025). "During the study, p-AKT, p-S6K1, and GLI1 expression levels decreased in tumor cells after NLRP3 knockdown." (PMID 39744485, 2025). "Research has found that tumor growth is significantly slowed by the use of NLRP3 antagonists or gene knockout techniques, accompanied by a substantial decrease in inflammatory factors." (PMID 40535567, 2025). "IL-18 deficiency due to NLRP3 loss can impair IFN-γ production as well as STAT1 activation, thereby increasing tumor burdens in CRC." (PMID 41291696, 2025). "Taken together, these data suggest that NLRP3 promotes Foxp3 expression in Th17 cells and facilitates their conversion into Tregs, thereby promoting tumor growth." (PMID 40195474, 2025). "TLR9 promotes tumor growth and increases chemoresistance by recognizing the specific domain of mtDNA, whereas activated NLRP3 triggers downstream signaling cascades and assembles inflammasomes via potassium ion efflux." (PMID 41246345, 2025). "NLRP3 enhances inflammation, stimulates angiogenesis, and promotes the proliferation and migration of tumor cells." (PMID 41378310, 2025). "In colorectal cancer (CRC), liver metastasis, fibrosarcoma, and lymphoma, NLRP3 inhibition suppresses tumor migration, while its activation promotes metastatic spread." (PMID 40155968, 2025).